EPHA2 (EPH receptor A2)
Diseases named in the same sentence as EPHA2 in open-access papers (continued):
Sharing a sentence is not in itself a finding about the gene and the disease.
breast cancer (continued). "In addition, we generated inducible overexpression of PTEN in PTEN-deficient cell lines, including SPAC-1-L and Ishikawa (EC lines) as well as HCC1937 (breast cancer) to demonstrate that EphA2 was downregulated in cancer cells with PTEN overexpression." (PMID 41130297, 2025). "To validate that the upregulation of EphA2 by PTEN loss is not restricted to a single cell line or breast cancer, we conducted PTEN siRNA knockdown in two different cancer cell lines: HCT116 (colorectal cancer) and PEO1 (ovarian cancer)." (PMID 41130297, 2025). "Notably, the expression of EphA2 protein and mRNA was correlated with lymph node metastasis, clinical stage, and histologic grade of breast cancer." (PMID 40236294, 2025). "Also, in molecular level analysis, EphB6 suppresses EphA2-promoted anoikis of breast cancer cells by interfering with EphA2-Ephexin 4 interaction." (PMID 40065768, 2025). "Additionally, we compared the differential expression of EPHA2 among various breast cancer cell lines of different subtypes." (PMID 40919148, 2025). "Interestingly, EphA2 is capable of maintaining stemness not only in breast cancer cells but also in cancers such as hepatocellular carcinoma and colorectal cancer, but its relationship with OSCC stemness has rarely been discussed." (PMID 38916835, 2024). "Among the diverse types of receptors within the Eph family, the EphA2 transformation of normal cells into malignant, angiogenesis, and metastasis has been comprehensively studied in many types of cancers, such as melanoma, glioblastoma, and breast cancer." (PMID 39525153, 2024). "EphA-2’s involvement in resistance mechanisms against trastuzumab therapy has also been documented, further validating its role as a key pro-tumorigenic antigen within the breast cancer landscape." (PMID 38612592, 2024). "Lastly, the EPHA2/ephrin-A1 signaling axis in regulating glutamine metabolism in HER2-positive breast cancer has been explored, with findings suggesting that ephrin-A1 loss leads to upregulated glutamine metabolism and lipid accumulation, enhancing tumor growth." (PMID 39408832, 2024). "Furthermore, EphA-2 is a more prominent pro-tumorigenic antigen in breast cancer than other Eph family members." (PMID 38612592, 2024). "An increase in the EphA2 level was induced by RNF5 shRNA in the three breast cancer cell lines, and the phosphorylation of EphA2 at S897 was decreased while that at Y772 was increased in RNF5 KD cells of all cell lines compared with the corresponding RNF5 WT cells (top)." (PMID 37816703, 2023). "EphA2 is a member of the Eph family, and high expression of EphA2 occurs in a variety of tumors, such as liver cancer, breast cancer, colorectal cancers, bladder cancer and glioblastoma, and EphA2 is a key driver of metastasis and a predictor of poor prognosis in several tumors." (PMID 37980165, 2023). "Furthermore, our results showed that combined inhibition of TrkA and EphA2 significantly reduced brain metastasis in a preclinical breast cancer model." (PMID 38072918, 2023). "Indeed, in breast cancer, ProNGF stimulation leads to the formation of the TrkA/EphA2/Sortilin complex, which induces the phosphorylation of Src through a pTrkA-independent mechanism." (PMID 37046604, 2023). "Interestingly, it was also observed that Src phosphorylation, which was induced in breast cancer cells that were in contact with the brain parenchyma, was suppressed when EphA2 expression was inhibited by siRNA in MDA-MB-231 cells." (PMID 38072918, 2023). "EPHA2, a member of the Eph kinase family, plays a crucial role in driving breast cancer metastasis." (PMID 38008720, 2023). "Furthermore, the monoclonal antibody EPhA2 can specifically target antigens and suppress the development of breast cancer cells and tumorigenesis." (PMID 37513835, 2023). "Additionally, the angiogenesis and metastasis of breast cancer are mediated by EPHA2 via AMPK signaling." (PMID 38008720, 2023).
breast cancer (continued). "Altogether, these results suggest that high EphA2 expression is associated with longer survival of HER2-negative breast cancers with low RNF5 expression, in which leads to that EphA2 acts as a tumor suppressor and improved prognosis under RNF5 inhibition in ER-positive HER2-negative breast cancers." (PMID 37816703, 2023). "It will be investigated whether pS897 EphA2-induced chemosensitivity is mediated by drug-resistance gene expression in breast cancer stem cells." (PMID 37063424, 2023). "It is shown that EPHA2 is highly expressed in breast cancer." (PMID 38008720, 2023). "Similarly, the EphA2-conjugated paclitaxel (PTXEphA2) loaded microspheres reduced the viability of the MDA-MB_231 breast cancer cells than the unconjugated paclitaxel (PTX)-loaded microspheres (p < 0.05) after 72 and 96 h." (PMID 37530973, 2023). "Another team reported that EPHA2 overexpression promotes breast cancer progression in synergy with HER2, suggesting that its therapeutic targeting could be of clinical value in HER2-positive mammary carcinomas." (PMID 35204461, 2022). "To investigate whether the kinase activity of EPHA2 is required for HM-Exos to promote angiogenesis, we treated endothelial cells with exosomes derived from LM and HM breast cancer cells." (PMID 35673569, 2022). "Our findings also suggest that the increased exosomal EPHA2 in the circulation may be an important mechanism for accelerating breast cancer progression and an indicator of tumor metastasis." (PMID 35673569, 2022). "Thus, our study identifies a novel mechanism of exosomal EPHA2-mediated intercellular communication from breast cancer cells to endothelial cells in the tumor microenvironment to provoke angiogenesis and metastasis." (PMID 35673569, 2022). "Their expression in breast cancer has been investigated using cell lines, animal models, and human tissue samples, and correlated with patients’ prognosis EPHA2, EPHB4, and EPHB6 are the receptors most extensively studied so far." (PMID 35204461, 2022). "Dimeric 123B9 peptide, targeting EphA2 (related to cancer metastasis, overexpressed in melanomas, ovarian, prostate, lung, and breast cancers), conjugated with paclitaxel inhibits lung metastasis in breast cancer models." (PMID 36364057, 2022). "Exosomal EPHA2 can be transferred from HM breast cancer cells to endothelial cells." (PMID 35673569, 2022). "Targeting the exosomal EPHA2-AMPK signaling may serve as a potential strategy for breast cancer therapy." (PMID 35673569, 2022). "In addition, the breast cancer tissues were divided into the low- and high-expression groups according to the expression levels of EPHA2." (PMID 35673569, 2022). "In this study, administration of sinomenine can effectively repress hypoxia-caused VM formation and migration of breast cancer SP cells, with the downregulation of VE-cadherin, MMP-9, and EphA2, which are all closely related to VM formation and metastasis of cancer cells." (PMID 35309179, 2022). "Collectively, our findings indicate that exosomal EPHA2 released by HM breast cancer cells may educate endothelial cells through paracrine action, promote angiogenesis and facilitate the establishment of a long-distance niche suitable for metastasis." (PMID 35673569, 2022). "Hence, these results suggest that a high level of EPHA2 in circulating exosomes is an indicator of breast cancer metastasis." (PMID 35673569, 2022). "Moreover, stimulation with EphA2-targeting siRNA highly decreases malignancy in glioma, breast cancer cells and non-small cell lung cancer (NSCLC)." (PMID 36142306, 2022). "Therefore, the role and mechanism of exosomal EPHA2 in regulating breast cancer angiogenesis and metastasis need to be identified." (PMID 35673569, 2022). "In fact, upon Odin silencing in MDA-MB-231 breast cancer cells a rapid decrease of EphA2 levels following ligand stimulation could be revealed thus confirming the protective role of Odin towards EphA2 degradation in cells." (PMID 36142306, 2022).
breast cancer (continued). "The exosomal EPHA2 can be transferred from HM breast cancer cells to endothelial cells." (PMID 35673569, 2022). "Herein, we found that EPHA2 is highly expressed in HM breast cancer cells and exosomes." (PMID 35673569, 2022). "In this study, we found that the exosomes produced by HM breast cancer cells were rich in EPHA2." (PMID 35673569, 2022). "Collectively, our results indicate that the increase of exosomal EphA2 may be an important mechanism of chemotherapy/drug resistance-induced breast cancer progression." (PMID 33879771, 2021). "Hence, the binding of exosomal EphA2 to Ephrin A1-induced reverse signaling promotes aggressive behavior in breast cancer." (PMID 33879771, 2021). "Consequently, exosomes from EphA2-expressing HEK-293T cells significantly promote the breast cancer cell migration and invasion ability compared with the control exosomes." (PMID 33879771, 2021). "Our study also suggests that the increase of EphA2 in drug-resistant cell-derived exosomes may be an important mechanism of chemotherapy/drug resistance-induced breast cancer progression." (PMID 33879771, 2021). "Collectively, these results suggested that exosomal EphA2 could promote breast cancer cell metastasis in vivo." (PMID 33879771, 2021). "Deregulated EphA2/Ephrin A1 signal is observed in many types of tumors, particularly breast cancer." (PMID 33879771, 2021). "EphA2 is a member of the Eph RTK family which is often overexpressed in aggressive breast cancers." (PMID 34414885, 2021). "Moreover, exosomes carrying EphA2-S897A also show a significant invasive promoting effect on breast cancer cells, indicating that the kinase-independent forward signaling is not involved in this effect." (PMID 33879771, 2021). "Our study also suggests that the increase of EphA2 in DR-Exos may be an important mechanism of chemotherapy/drug resistance-induced breast cancer progression." (PMID 33879771, 2021). "EPHA2 transcript levels are enriched in human breast cancer bone metastatic lesions relative to visceral metastatic sites; EphA2 protein expression was detected in breast tumor cells in bone metastases in patient samples, supporting the clinical relevance of the study's findings." (PMID 33869989, 2021). "Moreover, transwell assay showed that exosomes from EphA2-silenced cells disable the migratory and invasive promoting effect in breast cancer cells." (PMID 33879771, 2021). "Together, these data provide preclinical validation of EphA2 as a clinically relevant molecular target for breast cancer bone metastatic disease, warranting further investigation of molecular mechanisms that link EphA2 to tumor‐induced osteolysis and potential development of a clinical inhibitor." (PMID 33869989, 2021). "Moreover, the EphA2 levels in the plasma of breast cancer patients receiving chemotherapy were significantly higher than that at the time of initial diagnosis." (PMID 33879771, 2021). "Tumor necrosis factor receptor (TNFR) in chondrocytes, sortilin in breast cancer cells, cation-independent mannose 6-phosphate receptor in neuroblastoma cells, and EphA2 in human umbilical vein endothelial cells and bladder cancer cells also bind extracellular progranulin." (PMID 33490663, 2021). "We first established xenograft tumor models by subcutaneous injection of MDA-MB-468 cells, MDA-MB-468/EPR cells, control, and EphA2-stable knockdown cells into the fat pad of SCID mice to investigate the function of exosomal EphA2 on the metastatic potential of breast cancer cells in vivo." (PMID 33879771, 2021). "Hence, our results indicate that the exosomal transmission of EphA2 from drug-resistant cells to drug-sensitive cells plays an important role to promote the progression of breast cancer." (PMID 33879771, 2021). "Similarly, EphA2 is expressed in breast cancer tissue, and its elevated expression correlates with poor patient survival, particularly in triple-negative breast cancer (TNBC)." (PMID 34204178, 2021).
breast cancer (continued). "Nevertheless, the detailed mechanism, through which EphA2 contributes to breast cancer progression, remains largely unknown." (PMID 33879771, 2021). "This hypothesis is supported by our in vivo studies showing the efficacy of molecular/genetic and pharmacologic inhibition of EphA2 in reducing osteolytic disease in breast cancer bone allograft and xenograft experimental metastasis models." (PMID 33869989, 2021). "Furthermore, sortilin in breast cancer cells, cation-independent mannose 6-phosphate receptor in neuroblastoma cells, and EphA2 in human umbilical vein endothelial cells and bladder cancer cells have been reported to bind extracellular progranulin." (PMID 33490663, 2021). "Moreover, EphA2-rich exosomes from HEK-293T cells induced an apparent increase in p-ERK1/2 in breast cancer cells." (PMID 33879771, 2021). "Given the induction by Pparγ1 of EphA2, Amphiregulin, Adam12 in the mammary tumors we sought to determine whether PPARγ1 directly interacted in the context of chromatin with these target genes." (PMID 33946495, 2021). "In established cell line cultures, EphA2 expression was higher in cancer cells than in untransformed ones: increased staining intensity was observed, for example, in a large fraction of breast carcinoma cells (an average of 87%) when compared to benign mammary epithelial cells (an average of 3%)." (PMID 33572284, 2021). "Consistent with the current results, previous observations noted that EphA2 signaling protects breast cancer cells from death, EphB3 signaling suppresses Fas‐induced apoptosis in T cells, and the kinase inhibitor AZ12672857 reduces the viability of selected colorectal carcinoma cells." (PMID 31545551, 2019). "Given the overexpression of EphA2 in breast cancer cells, tumor suppressor action of EphB6 may be explained by its heteromerization with EphA2." (PMID 29682554, 2018). "Similar to breast cancer, EphA2 is the most extensively studied EphA receptor in prostate cancer." (PMID 29682554, 2018). "An inverse relationship between EphA2 and estrogen dependence has been observed in breast cancer cells both in vivo and in vitro, and decreased tamoxifen sensitivity was noticed in estrogen receptor (ER) positive breast cancer cells with EphA2 overexpression." (PMID 29682554, 2018). "EphA2 and EphB4 are the two most extensively studied receptors in breast carcinomas." (PMID 29682554, 2018). "EphA2/ErbB2 complex is important in promoting breast cancer but the mechanism by which these receptor tyrosine kinases are exported from the endoplasmic reticulum is unknown." (PMID 27619642, 2016). "As an illustrative example the mutual exclusivity pattern of the union of these networks is shown for EPHA2, one of the prioritized genes that was rarely mutated in breast cancer and not listed in any of the used reference cancer databases." (PMID 27808240, 2016). "We next used the SK-BR-3 human breast cancer cell line with ErbB2 amplification to see whether Anks1a plays a role in EphA2-mediated ErbB2 signalling." (PMID 27619642, 2016). "Down regulation of Ephrin A1 in breast cancer increases tumor invasiveness illustrating that this may be a way to maintain EphA2 Ser897 phosphorylation." (PMID 27533087, 2016). "Thus EphA2 localization in breast cancer cells has been found to be controlled by E-cadherin and Ephrin B3 was reported to influence EMT via the small GTPase Rac in glioma cells." (PMID 27533087, 2016). "Furthermore, lack of E-cadherin-dependent cell-cell adhesion can impair EphA2 receptor activation in breast cancer cells, suggesting inefficient EphA2 trans interaction with ephrins." (PMID 24348920, 2013). "EphA2 leads to growth arrest and differentiation in normal human mammary epithelial cells in three-dimensional cultures, and its level was significantly decreased in the differentiated cells, whereas the expression increased in breast cancer." (PMID 24705208, 2013).
breast cancer (continued). "Moreover, EphA2 overexpression decreased the ability of tamoxifen to inhibit breast cancer cell growth and tumorigenesis." (PMID 22417809, 2012). "The finding in this study that EphA2 was overexpressed in a tamoxifen resistant cell line confirms the involvement of the receptor tyrosine kinase in the development of tamoxifen resistance in breast cancer." (PMID 22417809, 2012). "These analyses confirmed the relevance of EphA2 and EphB4 to human breast cancer progression, and uncovered significant correlations for EphA4, EphA7, and EphB6, which were previously under-investigated in breast cancer." (PMID 21935409, 2011). "We evaluated protein expression of EphA2, EphA4, EphA7, EphB4, and EphB6 in human breast cancer tissue microarrays (TMA) in which we could distinguish expression in tumor epithelium from stromal components, including endothelium." (PMID 21935409, 2011). "The inhibition of EphA2 couldbe advantageous in cancer therapy whenever EphA2 activation mediates tumorprogression as previously demonstrated on mammary tumors and melanoma cells.Currently, many strategies to block EphA2 signaling have been explored." (PMID 21479221, 2011). "Additionally, EphA2, a target of dasatinib, is a candidate predictor of efficacy in both prostate and breast cancer." (PMID 18047674, 2007). "Notably, EphA2, a dasatinib target, was significantly correlated with dasatinib sensitivity in both prostate and breast cancer cell lines." (PMID 18047674, 2007). "Also, the interaction of EphB6 and EphA2 has been observed in breast cancer cell lines." (PMID 40065768, 2025). "Importantly, a fragment of the intracellular domain of HER2, termed 611-CTF (carboxy terminal fragment), can constitutively homodimerize and regulate MET, EPHA2, matrix metalloproteinase 1, interleukin 11, angiopoietin-like 4, and different integrins, promoting mammary tumor growth and metastasis." (PMID 37138747, 2023). "The aim of breast cancer therapy may be to merge EphA2 expression with carcinogenesis." (PMID 37513835, 2023). "Consequently, RNF5 inhibition increases the adhesion and decreases the migration of HER2-negative breast cancer cells, and RNF5 silencing suppresses the growth of xenograft tumors derived from ER-positive, HER2-negative breast cancer cells with increased EphA2 expression and altered phosphorylation." (PMID 37816703, 2023). "Hence, we hypothesized that Shc3 might act as a novel adaptor between EphA2 and ErbB2 in breast cancer cells." (PMID 36880347, 2023). "Furthermore, their findings propose that increased EPHA2 in drug-resistant cell-derived exosomes could present a principal mechanism of chemotherapy/drug resistance-induced breast cancer progression." (PMID 35408909, 2022). "Nevertheless, the functional significance of the exosomal EPHA2 in breast cancer remains unclear." (PMID 35673569, 2022). "Therefore, we measured the agonistic EphA2 activity of 135H11-biotin (147B5) at various agent/streptavidin ratios, side by side with 135H12, and a scrambled version of 147B5 in pancreatic- and breast-cancer cell lines." (PMID 34204178, 2021). "In addition, exosomes carrying EphA2-ΔS and EphA2-S897A could promote the migration and invasion of breast cancer cells, which were similar to exosomes carrying EphA2." (PMID 33879771, 2021). "Thus, it is possible that EphA2 and its ligands may interact and mediate osteoclastogenesis in breast cancer bone metastatic disease through functions in the host bone microenvironment." (PMID 33869989, 2021). "For example, we previously demonstrated that synthetic EphA2-targeting agonistic agents conjugated with gemcitabine or paclitaxel had superior efficacy compared to gemcitabine or paclitaxel alone in mouse models of pancreatic cancer and breast cancer, respectively." (PMID 34204178, 2021).